CDCP1 (CUB domain containing protein 1)
Description:
May be involved in cell adhesion and cell matrix association. May play a role in the regulation of anchorage versus migration or proliferation versus differentiation via its phosphorylation. May be a novel marker for leukemia diagnosis and for immature hematopoietic stem cell subsets. Belongs to the tetraspanin web involved in tumor progression and metastasis.
Synonyms: SIMA135; CD318; TRASK
Tractability: Antibody: UniProt places it where antibodies can reach, with high confidence; UniProt predicts a signal peptide or a membrane-spanning region; its Gene Ontology location is reachable by antibodies, with medium confidence. PROTAC: ubiquitination databases record sites on it.
Gene: Protein-coding gene on chromosome 3 (45,082,277 to 45,146,453, reverse strand). Ensembl gene ENSG00000163814.
Subcellular location: Cell membrane (Isoform 1); Secreted (Isoform 3)
Subcellular location (Human Protein Atlas): Nucleoplasm; Vesicles; Nuclear bodies
Gene Ontology:
Molecular function: protein binding
Cellular component: extracellular region; plasma membrane
Genetic constraint (gnomAD): Loss-of-function variants: 27 observed, 61.94 expected, observed/expected ratio (o/e) 0.44, 90% interval 0.32 to 0.6. The upper end of that interval is the gene's LOEUF score, 0.6, which puts it in group 2 of 6, group 1 being the genes least tolerant of losing a copy. Missense variants: 827 observed, 1,070 expected, observed/expected ratio (o/e) 0.77, 90% interval 0.73 to 0.82. Synonymous variants: 369 observed, 432.1 expected, observed/expected ratio (o/e) 0.85, 90% interval 0.78 to 0.93.
Homologues: Orthologues: chimpanzee CDCP1 (99% identical), macaque CDCP1 (96% identical), dog CDCP1 (85% identical), pig CDCP1 (82% identical), mouse Cdcp1 (81% identical), rat Cdcp1 (81% identical), rabbit CDCP1 (78% identical), guinea pig CDCP1 (69% identical), tropical clawed frog cdcp1 (43% identical), zebrafish CDCP1 (26% identical), zebrafish cdcp1a (21% identical).
Diseases named in the same sentence as CDCP1 in open-access papers:
CDCP1 is named in the same sentence as 130 diseases in open-access papers, as found by Europe PMC text mining. Sharing a sentence is not in itself a finding about the gene and the disease. The quoted sentences say what the papers report.
lung carcinoma (35 papers, 2012 to 2025). "For example, we replicated the association of CDCP1 with lung cancer risk reported within the EPIC cohort and also found concordant evidence for risk proteins, such as CEACAM5, identified within up to three years before diagnosis in the INTEGRAL project." (PMID 38750076, 2024). "In our study, CDCP1 expression was associated with recurrence and death in patients undergoing surgery for lung cancer." (PMID 35054034, 2022). "A disintegrin and metalloprotease 9 (ADAM9) and CUB-domain-containing protein 1 (CDCP1) are both oncogenic membrane proteins associated with lung cancer metastasis." (PMID 28537886, 2017). "However, CDCP1 expression in stage I lung cancer was significantly associated with recurrence within 5 years after surgical resection." (PMID 35054034, 2022). "CDCP1 has been implicated to be highly expressed in many kinds of cancer cells, and to be related to over-proliferation, migration, invasion, and lymph node metastasis of lung cancer." (PMID 31417870, 2019). "CUB ((C1r/C1s, urchin embryonic growth factor, BMP1) domain containing protein 1, CDCP1) is a type I transmembrane protein, which has been reported in several malignancies such as lung cancers and breast tumors, mostly associated with poor prognosis and disease progression." (PMID 24905404, 2014). "In a subsequent study, they proposed that ADAM9 inhibits miR-1 through activation of epidermal growth factor receptor, thereby enhancing the role of CDCP1 in lung cancer metastasis." (PMID 39441449, 2024). "Senescence cells accumulated when lung cancer cells were treated with 8PN but a slight reduction in CDCP1 knockdown cells with 8PN treatment." (PMID 37013960, 2023). "This suggests that 8PN targets CDCP1 and acts via multiple alternative necrotic lung cancer cell death pathways, including apoptosis, necroptosis, and pyroptosis." (PMID 37013960, 2023). "8‐isopentenylnaringenin (8PN) was identified as a CDCP1 reducer to suppress CDCP1 proteins via lysosomal degradation and reduced lung cancer progression." (PMID 37013960, 2023). "CUB domain‐containing protein 1 (CDCP1) contributes to epidermal growth factor receptor (EGFR) tyrosine kinase inhibitor (TKI) resistance in lung cancer treatment." (PMID 37013960, 2023). "In the present study, we identified 8PN, a natural compound, as a CDCP1 inhibitor to suppress lung cancer progression." (PMID 37013960, 2023). "Detected signals, representing the HA‐tagged CDCP1 levels on the surface of lung cancer cells, were compared between the treated samples and the untreated control group." (PMID 37013960, 2023). "Elevated cleaved CDCP1 proteins were detected in brain‐metastatic lung cancer and breast cancer sublines compared with their parental cells." (PMID 37013960, 2023). "In summary, 8PN, a natural compound, was identified as a CDCP1 inhibitor that can attenuate lung cancer cell malignancy." (PMID 37013960, 2023). "Increased expression of AXL and CDCP1 was observed in refractory tumor samples from patients with lung cancer treated with osimertinib." (PMID 35643725, 2022). "CDCP1 was first identified as a highly upregulated gene in colorectal and lung cancer and has emerged as a driver of tumorigenesis and metastasis across a wide range of indications." (PMID 35166238, 2022). "While previous work has suggested a connection between RAS signaling and CDCP1 in lung cancers, our work now demonstrates MAPK signaling-dependent expression of this protein in multiple epithelial-derived RAS-driven malignancies as well as in vivo." (PMID 29359686, 2018). "Inhibition of ADAM9 protein expression or protease activity rescued miR-1 suppression and down-regulated expression of its target CDCP1 in lung cancer cells." (PMID 28537886, 2017). "A consistent pattern of decreased CDCP1 in pri-mir-1-transfected cells was observed in different lung cancer cell lines, such as Bm7, and H1299." (PMID 28537886, 2017).
lung carcinoma (continued). "ADAM9 promotes lung cancer metastasis through increase of CDCP1 expression and activation of CDCP1 function." (PMID 28537886, 2017). "In summary, we found that ADAM9 controls CDCP1 function by increasing its expression and activity, which results in lung cancer metastases." (PMID 28537886, 2017). "miR-1 expression was down-regulated in lung tumors, but increased in ADAM9-knockdown lung cancer cells, and was negatively correlated with CDCP1 expression as well as the migration ability of lung cancer cells." (PMID 28537886, 2017). "In our previous study, we found that ADAM9 enhanced lung cancer migration by up-regulating CDCP1 and that blocking the two proteins reduced lung cancer metastasis." (PMID 28537886, 2017). "We found that ADAM9 also down-regulated several other miRNAs, such as miR-766 and miR-612, that target CDCP1 in lung cancer cells." (PMID 28537886, 2017). "When CL1-0 and A549 lung cancer cells were treated with a miR-1 inhibitor, both CDCP1 RNA levels and CDCP1 protein levels were dramatically increased." (PMID 28537886, 2017). "Next, human influenza hemagglutinin (HA) tagged CDCP1 (HA-CDCP1) was overexpressed in lung cancer F4 cells." (PMID 26553452, 2015). "Several genes are reported to be associated with lung cancer metastasis, such as ADAM9 (a disintegrin and metalloprotease 9) and CDCP1 (CUB-domain-containing protein 1)." (PMID 26553452, 2015). "Previously, we found that ADAM9-depleted lung cancer cells decreased CDCP1 expression and cell migration." (PMID 26553452, 2015). "Binding to CDCP1 by our antibodies was confirmed by flow cytometry on NCI-H358 lung cancer cells, where siRNA knock-down of CDCP1 reduced the level of antibody binding, and by direct ELISA performed using recombinant full-length CDCP1." (PMID 26227951, 2015). "Conversely, when lung cancer cells were treated with miR-218 antagomirs, levels of miR-218 were decreased, but the amount of CDCP1 protein was increased in lung cancer cells at 48 h after miR-218 antagomirs transfection." (PMID 26553452, 2015). "CDCP1 mRNA was first identified as up-regulated, compared to normal lung tissue, in the lung cancer cell line A549 and so this cell line was included for comparison." (PMID 25301083, 2014). "LC3II protein levels were shown to increase for lung cancer cells with knock down of CDCP1 levels and the increased autophagy was confirmed by GFP-LC3 foci formation." (PMID 24905404, 2014). "z-VAD-Fmk, a general inhibitor of caspase, did not have any effect on the cell death caused by knock down of CDCP1, confirming that cell death being induced in lung cancer cells by inhibition of CDCP1 signaling is caspase independent." (PMID 24905404, 2014). "However, the ADAM9/CDCP1/t-PA pathway and their aberrant expressions have so far been human lung adenocarcinoma cell lines and lung cancer." (PMID 39441449, 2024). "We knocked down CDCP1 using lentiviral shRNA in lung cancer cells." (PMID 37013960, 2023). "CDCP1 was also identified as a transmembrane glycoprotein that plays a role in migration/invasion events of various cancers, including colorectal, pancreatic, ovarian, gastric, breast, prostate, melanoma, renal cell carcinoma, and lung cancers." (PMID 36862682, 2023). "Next, we investigated whether 8PN‐mediated CDCP1 reduction can increase the sensitivity to EGFR TKI in EGFR TKI‐resistant lung cancer cells, including H1650 (EGFR exon 19 deletion and PTEN mutant) and H1975 (EGFR L858R) cells." (PMID 37013960, 2023). "Moreover, we found that 8PN induced cell senescence in lung cancer cells, consistent with the report that overexpression of CDCP1 bypasses senescence to increase prostate cancer cell proliferation." (PMID 37013960, 2023). "Owing to the effects of 8PN on CDCP1 protein downregulation, we sought to examine whether 8PN could influence the migration ability of lung cancer cells using a time‐lapse migration assay." (PMID 37013960, 2023).
lung carcinoma (continued). "Together, our results revealed that 8PN reduced CDCP1 proteins and alleviate lung cancer growth." (PMID 37013960, 2023). "We also found that EGFR TKIs enhanced IL6 mRNA expression in CDCP1 knockdown lung cancer cells." (PMID 37013960, 2023). "Moreover, the knockdown of CDCP1 in lung cancer cells significantly lowered the cell viability upon EGFR TKI treatment compared with TKI treatment alone." (PMID 37013960, 2023). "On the other hand, previous studies have reported that enhanced AXL expression is often associated with acquired resistance to osimertinib in lung cancer cells, and also that enhanced expression of both AXL and CDCP1 is associated with poor outcomes of patients with NSCLC23." (PMID 35643725, 2022). "In osimertinib-resistant lung cancer cell lines harboring T790M mutation that we established, expression of multiple EGFR family proteins and MET was markedly reduced, whereas expression of AXL, CDCP1 and SRC was augmented along with activation of AKT." (PMID 35643725, 2022). "Thus, ADAM9 promotes the CDCP1 activation for lung cancer metastases to the brain through a tPA-based pathway." (PMID 33096780, 2020). "Interestingly, infraexpression of CDCP1 targeting miRNAs miR-654 and miR-218 in ovarian and lung cancers, respectively, has been reported." (PMID 32817447, 2020). "Moreover, miRNA-1 negatively correlates with CDCP1 expression and with migration ability of lung cancer cells." (PMID 29868480, 2018). "Our previous study demonstrated that ADAM9 promotes lung cancer metastasis by enhancing the function of CDCP1 and regulates the expression of several genes through dysregulation of miRNAs, such as activation of N-cadherin (CDH2; cadherin 2) and CDCP1 through miR-218." (PMID 28537886, 2017). "The resulting high levels of CDCP1 can promote the migration of lung cancer cells." (PMID 28537886, 2017). "Thus, the results indicated that ADAM9 can reduce miR-1 levels and increase CDCP1 expression in lung cancer cells." (PMID 28537886, 2017). "Furthermore, miRNA-1 demonstrated a negative association with CDCP1 expression and the migratory capacity of lung cancer cells." (PMID 41416095, 2025). "Moreover, our immunohistochemical findings further revealed significantly increased expressions of CDCP1 and t-PA in OSCC, which correspond with CDCP1 overexpression in renal cell carcinoma and in lung adenocarcinoma and with t-PA overexpression in lung cancer." (PMID 39441449, 2024). "To develop potential CDCP1 inhibitors, we performed high‐throughput drug screening with a cell‐based platform and identified a prenylated flavonoid, 8‐isopentenylnaringenin (8PN), as a potential agent to suppress CDCP1 expression and influence lung cancer progression." (PMID 37013960, 2023). "Also, silencing ADAM9 or CDCP1 in lung cancer Bm7 cells decreased their migration." (PMID 26553452, 2015). "We confirmed that full‐length CDCP1 proteins were exclusively reduced, although a small portion of the cleaved CDCP1 was detected by treating mouse lung cancer TC1 cells and human lung cancer Bm7 cells with 8PN." (PMID 37013960, 2023). "A previous study showed that the ADAM9-CDCP1 signaling pathway plays a role in the progression of lung cancer and ADAM9 enhances CDCP1 expression in lung cancer cell lines." (PMID 33260155, 2020). "Consistent with this, we found that EGF stimulation increases CDCP1 expression and EGFR inhibitor reduces the level of CDCP1 in lung cancer cells." (PMID 28537886, 2017). "Although this involves a switch to a prostate cell line in place of lung cancer primary cells, which may be disadvantageous in translating the molecular effects of some antibodies in the panel, the invasive phenotype exhibited proved to be a useful platform for comparing our anti-CDCP1 molecules." (PMID 26227951, 2015).
lung carcinoma (continued). "CUB domain‐containing protein 1 (CDCP1) contributes to epidermal growth factor receptor (EGFR) tyrosine kinase inhibitor (TKI) resistance by regulating EGFR signaling pathways and is a potential target in lung cancer treatment." (PMID 37013960, 2023). "ADAM9 and CDCP1 were reported to show increased expression in cells with progressive migration ability (CL1-0 < F4 < Bm7brm) from the same original tumor; we found that miR-1 expression was lower in the lung cancer cells with greater migration." (PMID 28537886, 2017). "However, CDCP1 levels and EGFR signaling, as indicated by phospho-EGFR expression, were dampened in ADAM9-knockdown lung cancer cells, and ADAM9-knockdown cells showed more sensitivity to EGFR inhibitor treatment (Tarceva) than control cells (shGFP)." (PMID 28537886, 2017). "Studies in vitro have shown an anti-cancer function of miR-218, and the down-expression of miR-218 increases myocyte enhancer factor 2D (MEF2D) levels by promoting lung cancer growth, and by inhibiting NSCLC proliferation and metastasis via by downregulating CDCP1." (PMID 28915579, 2017). "Recently, CUB domain-containing protein 1 (CDCP1), a transmembrane glycoprotein, has been linked to a noble pathway of anoikis resistance independent of Ras-MAPK and PI3K-Akt pathways in lung cancer and gastric cancer cell lines." (PMID 22505926, 2012). "The ADAM9-CDCP1 axis was confirmed to be necessary for lung cancer cell migration and survival in vitro and in vivo; and moreover, the authors demonstrated that ADAM9 decreases the expression of miR-1 and miR-218, which target the 3′-UTR of CDCP1 to suppress its expression." (PMID 33096780, 2020).
breast carcinoma (29 papers, 2010 to 2025). "Elevated expression of CDCP1 is associated with poor overall survival of patients with cancer of the breast 18-20, colorectum 21, kidney 22, lung 23, ovary 13,24 and pancreas 25 while a potential protective role has been recently identified in prostate cancer." (PMID 32226543, 2020). "In other studies, CDCP1 expression induced loss of cell adhesion to standard tissue culture plates in the MDA-468 breast cancer cell line." (PMID 25301083, 2014). "In conclusion, our studies in breast cancer cell lines identified the CDCP1-SRC-ARHGEF7-RAC1 axis as a crucial mediator of HGF-induced cancer cell migration and invasion." (PMID 35085554, 2022). "Altogether, these results demonstrate that the CDCP1-SRC-ARHGEF7-RAC1 pathway plays an important role in the HGF-induced invasion of a subset of breast cancer cells." (PMID 35085554, 2022). "Here, we show that HGF-promoted migration and invasion of breast cancer cells are regulated by CUB domain–containing protein 1 (CDCP1), a transmembrane activator of SRC kinase." (PMID 35085554, 2022). "We investigated the role of CDCP1 in human breast cancer cells and found that the CDCP1-SRC axis enhanced the HGF-induced formation of lamellipodia or membrane ruffles, leading to the promotion of cell migration and invasion." (PMID 35085554, 2022). "Among the candidate CpGDMs, we found eight genes with differential methylation previously associated with breast cancer susceptibility and pathology in the G2SBC and COSMIC Databases (AMOTL1, CDCP1, CYFIP1, MAP3K6, MIB2, SDK1, TAL1, and TYROBP)." (PMID 33145876, 2021). "Secondly, in breast cancer, the expression of CDCP1 mRNA and proteins were differential: high in the tumor tissues and low in adjunct normal tissues." (PMID 32308755, 2020). "CDCP1 (CUB-domain containing protein 1) is a stem cell marker which has been shown to be regulated by epigenetic mechanisms in breast cancer cell lines as well as in clinical findings." (PMID 31320814, 2019). "The correlation that we observed between a gain in CDCP1 copy number and the number of cells that express CDCP1 in TNBCs supports that CDCP1 polysomy is involved in CDCP1 overexpression in this breast cancer subtype." (PMID 29792166, 2018). "Another powerful example of the role of CDCP1 in mediating poor response to therapy involves breast cancer resistance to the HER2 targeted therapeutic antibody trastuzumab." (PMID 26973855, 2016). "As reported for the MDA-MB-231, T47D, and MDA-MB-468 breast cancer cell lines, CDCP1 expression and their migration and invasion in vitro were significantly associated." (PMID 27626701, 2016). "A probable pathway in breast cancer included CDCP1 that has known function in cell migration and cell matrix attachment." (PMID 27167193, 2016). "In this study, by stimulating TNBC cells with postsurgery wound-healing fluids (WHFs) from breast cancer patients to mimic a protumorigenic microenvironment, we identified CDCP1 as the only membrane receptor that was significantly upregulated." (PMID 27626701, 2016). "In contrast, when the HER2-positive BT474 breast cancer cell line was employed in the same experiment, EGFR was barely detectable in association with CDCP1, but HER2 robustly associated with a mimetic of the cleaved form of CDCP1 (ΔCDCP1)." (PMID 27495374, 2016). "In the MDA-MB-468 breast cancer cell line, enforced CDCP1 expression induces cell detachment and growth in suspension even in the presence of a suitable adhesive substrate." (PMID 27495374, 2016). "Enforced CDCP1 overexpression in the MDA-MB-468 breast cancer cell line induces cell detachment from the substratum, cell proliferation and survival in suspension." (PMID 27495374, 2016). "Selection for cisplatin resistance in the A2780 ovarian cancer cell line led to decreased DNA hypermethylation around the CDCP1 gene, while DNA methylation near the CDCP1 gene promoter region negatively correlates with CDCP1 protein levels in breast cancer." (PMID 26227951, 2015).